TEX28 (testis expressed 28)
Synonyms: CXorf2; fTEX; MRX99
Tractability: Antibody: UniProt predicts a signal peptide or a membrane-spanning region.
Gene: Protein-coding gene on chromosome X (154,271,265 to 154,295,853, reverse strand). Ensembl gene ENSG00000278057.
Subcellular location: Membrane
Gene Ontology:
Molecular function: protein binding
Cellular component: endomembrane system; membrane
Homologues: Orthologues: chimpanzee TEX28 (99% identical), pig TEX28 (64% identical), dog TEX28 (63% identical), rabbit TEX28 (61% identical), mouse Tex28 (59% identical), rat Tex28 (57% identical), Drosophila melanogaster Dmtn (22% identical), Caenorhabditis elegans C15H9.4 (16% identical). Paralogues in human: TMCC1 (31% identical), TMCC2 (31% identical), TMCC3 (27% identical).